CCR1 (C-C motif chemokine receptor 1)
Diseases named in the same sentence as CCR1 in open-access papers (continued):
Sharing a sentence is not in itself a finding about the gene and the disease.
pancreatic cancer (6 papers, 2017 to 2025). "Of note, our previous assessment of pancreatic TAMs identified CCR1 as a key mediator of immune suppression in pancreatic tumors." (PMID 35156921, 2022). "Similar results were observed for STAT3 phosphorylation on serine-727 and CCR1 mRNA expression in T24 bladder and Capan-1 pancreatic cancer cells expressing AKT1 shRNA." (PMID 29212252, 2017). "Similarly, knockdown of STAT3 in T24 bladder cancer cells and Capan-1 pancreatic cancer cells dramatically decreased CCR1 mRNA levels, as revealed by RT-PCR and Q-PCR." (PMID 29212252, 2017). "Database analyses also revealed a significant negative correlation between ITGB4 and PTPRC (CD45 gene), CCR5 as well as CCR1 in pancreatic cancer, but not normal pancreas tissue." (PMID 36932441, 2023). "Finally, the TCGA and GTEx databases were used to verify a weak, but significant inverse correlation of CD45 (PTPRC gene), CCR5 and CCR1 with ITGB4 in human pancreatic cancer, but not normal pancreas." (PMID 36932441, 2023).
systemic candidiasis (6 papers, 2012 to 2022). "A genetic deficiency in mice for CCR1 showed diminished renal tissue injury and improved survival in a mouse model infected with candidiasis." (PMID 35399952, 2022). "Nevertheless, in other studies CCR1 knockout mice show, in the late phase of invasive candidiasis, impaired accumulation of neutrophils in the kidney associated with improved renal function and survival without impact on tissue fungal burden." (PMID 28797245, 2017). "In contrast, neutrophil accumulation was Ccr1-independent throughout the entire course of invasive candidiasis in the spleen, liver and brain." (PMID 22916017, 2012). "Also, because Ccr1 is expressed on neutrophil precursors and mature neutrophils in the bone marrow, the impact of Ccr1 deficiency in neutrophil precursor production and egress of neutrophils from the bone marrow to the blood after Candida infection merits further investigation." (PMID 22916017, 2012). "For instance, mice lacking the chemokine receptor Ccr1, which is critical for neutrophil recruitment, display improved renal function during invasive candidiasis and administration of Ccr1 antagonists reduces renal tissue injury and improves survival in mice challenged with systemic candidiasis." (PMID 29755472, 2018). "Hence, we first looked at the expression of Ccr1 in blood neutrophils of Ccr1+/+ mice during invasive candidiasis." (PMID 22916017, 2012). "Hence, these data show that Ccr1 expression increases on the surface of neutrophils in the blood and kidney late in the course of invasive candidiasis, when neutrophil accumulation is decreased in Ccr1−/− kidneys." (PMID 22916017, 2012). "Although differential dynamics in induction were observed among them, all Ccr1 ligands were significantly induced at the mRNA and protein levels in both Ccr1+/+ and Ccr1−/− kidneys (but not spleen) both early and late after invasive candidiasis." (PMID 22916017, 2012).
Alzheimer disease (5 papers, 2019 to 2023). A progressive, neurodegenerative disease characterized by loss of function and death of nerve cells in several areas of the brain leading to loss of cognitive function such as memory and language. "CCR1-mediated signal transduction is critical for the recruitment of effector immune cells to cause neuroinflammation and is an early and specific marker of Alzheimer's disease." (PMID 33424980, 2020). "RANTES (CCL5), an endogenous ligand of CCR1, has pro-inflammatory effects in animal models of cerebral ischemia, Alzheimer’s disease, and autoimmune encephalomyelitis (EAE)." (PMID 35062973, 2022).
colitis (5 papers, 2021 to 2024). Inflammation of the colon. "Furthermore, after 3 days of colitis induction, the gene expression of Ccr1 and Ccr2 was significantly decreased in the animals from the CβGl+ group compared to the rats from the CβG− group." (PMID 35163326, 2022). "After 7 days of induced colitis, upregulation of the expression of 22 genes (Ccl2, Ccl3, Ccl4, Ccl5, Ccl6, Ccl7, Ccl12, Ccl17, Cxcl1, Cxcl2, Cxcl6, Cxcl9, Cxcl11, Ccr1, Ccr2, Ccr3, Ccr5, Ccr8, Cxcr2, Csf3, Osm, and Spp1) was observed in the CβG− group compared to the HβG- control group." (PMID 35163326, 2022). "For L. acidophilus FGSYC48L79, although it blocked the CCL2/CCR2 axis, it can promote the signal transmission on the CCL3/CCR1 axis, which may be one of the reasons why this strain appeared to have the effect of worsening colitis." (PMID 36499169, 2022). "Therefore, blocking the signal transmission in CCL2/CCR2 axis and CCL3/CCR1 axis might be an important method for L. acidophilus FAHWH11L56 to potentially relieve colitis." (PMID 36499169, 2022). "As shown by ANOVA, the gene expression of Ccr1, Ccr2, Ccr5, and Cxcr2 was higher in the rats with TNBS-induced colitis than in the control group (p < 0.001)." (PMID 35163326, 2022). "Patients with IBD have increased CCL2 expression level, and CCL5 attracts CCR1 and CCR5-expressing inflammatory cells into colon tissue of trinitrobenzene sulphonic acid (TNBS)-induced colitis mice model." (PMID 36518763, 2022). "The gene expression of Ccr2, Ccr5, and Cxcr2 was increased in colitis rats fed with feed without beta-glucan (βG−) compared to the control group (HβG−) at both time points, whereas Ccr1 gene expression was increased only after 3 days of TNBS administration." (PMID 35163326, 2022). "Moreover, L. acidophilus NCFM and FAHWH11L56 showed similar effects on various indicators of DSS-induced colitis, increasing the IL-10 and IL-17 in the colon, and modifying the CCL2/CCR2 axis and CCL3/CCR1 axis." (PMID 36499169, 2022). "Accordingly, we observed that the expression levels of genes encoding chemokines (Ccl3, Ccl4, and Ccl6), chemokine receptors (Ccr1, Ccr5, Cxcr2, Cxcl1, Cxcl2, and Cxcl13), and inflammatory factors (Mpo, Il-1β, and Il12) were increased in mice with DSS-induced colitis." (PMID 34795650, 2021).
invasive candidiasis (5 papers, 2012 to 2021). "Our data show that Ccr1 plays a pathogenic role in invasive candidiasis by mediating renal immunopathology via excessive neutrophil recruitment from the blood into the kidney." (PMID 22916017, 2012). "Thus, we next investigated the mechanism(s) underlying the late Ccr1-dependent phase of neutrophil accumulation in the kidney after invasive candidiasis." (PMID 22916017, 2012). "Hence, identification of Ccr1, Ifnar1, and other molecular factors that mediate pathogenic neutrophil effects in invasive candidiasis could potentially lead to targeted therapeutic interventions in selected patients." (PMID 23300452, 2013). "Together these data demonstrate that neutrophils, besides their recognized protective roles in antifungal host defense, may also exert detrimental effects by causing uncontrolled tissue damage, and identify Ccr1 as a mediator of neutrophil tissue injury in a mouse model of invasive candidiasis." (PMID 22916017, 2012). "Our study is the first to identify a single molecular factor, Ccr1, as one of the mediators of immunopathology in the mouse model of invasive candidiasis." (PMID 22916017, 2012). "For the remainder of this paper, we focus our analysis on the role of Ccr1 in the pathogenesis of invasive candidiasis, as Ccr1 and its ligands were among the phagocyte-targeted chemotactic factors that were most highly induced in the model." (PMID 22916017, 2012). "In separate experiments, induction of Ccr1 and its ligands Ccl3, Ccl5, Ccl6, Ccl7, Ccl8 and Ccl9 by invasive candidiasis was examined in greater detail in mice injected with 1.25×105 CFU of C. albicans, which causes ∼80% mortality by day 14 post-infection." (PMID 22916017, 2012). "Of interest, Ccr1 mediated neutrophil accumulation in the kidney only late in the course of invasive candidiasis." (PMID 22916017, 2012). "Thus, neutrophil Ccr1 amplifies late renal immunopathology and increases mortality in invasive candidiasis by mediating excessive recruitment of neutrophils from the blood to the target organ." (PMID 22916017, 2012). "The mechanism of Ccr1-mediated neutrophil accumulation and immunopathology in the kidney in invasive candidiasis appears to lie at the level of neutrophil trafficking from the blood into the kidney, as shown by our competitive repopulation study using Ccr1+/+ and Ccr1−/− neutrophils." (PMID 22916017, 2012). "Because Ccr1 is expressed on neutrophils and monocytes/macrophages, which are critical for survival after invasive candidiasis, and since Ccr1 and its ligands were induced in the model, we investigated the in vivo role of Ccr1 in the pathogenesis of invasive candidiasis using Ccr1−/− mice." (PMID 22916017, 2012). "First, Ccr1 deficiency did not affect tissue Candida proliferation, an established correlate of survival in previous studies in the model of invasive candidiasis." (PMID 22916017, 2012). "Hence, it is plausible that availability of soluble or membrane-bound β-glucan late after invasive candidiasis may contribute to Ccr1 induction on neutrophils." (PMID 22916017, 2012). "Three important new questions arise from this finding: the first relates to the signals responsible for Ccr1 induction on neutrophils late but not early in the course of invasive candidiasis." (PMID 22916017, 2012). "However, in contrast to neutrophils, Ccr1 expression on the other myeloid cells was constant throughout the course of invasive candidiasis (data not shown)." (PMID 22916017, 2012). "In addition, neutrophil accumulation was Ccr1-dependent only in the kidney but not in the other organs examined, further attesting to the organ-specific nature of the innate immune response in invasive candidiasis." (PMID 22916017, 2012).
liver cancer (5 papers, 2022 to 2025). An epithelial or non-epithelial malignant neoplasm that arises from the liver. "Through single-cell data analysis, we identified specific expression of the chemokine CCL16 in liver cancer cells, while its receptor CCR1 was specifically expressed in macrophages." (PMID 38274805, 2023). "Together with CCL7, CCL5 activates chemokine receptor 1 (CCR1), which was found to promote liver cancer by inducing myeloid cell infiltration and angiogenesis." (PMID 35585513, 2022). "Through their interaction with specific receptors, such as CCR1, CCR2, CCR3, etc., these chemokines play a crucial role in the evolution of liver cancer." (PMID 40062588, 2025).
lupus (5 papers, 2016 to 2024). "CCR1 inhibition with the oral antagonist BL5923 has been tested in murine lupus demonstrating reduced T cell and macrophage infiltration in the kidneys and significant clinical improvement." (PMID 38899167, 2024). "In lupus-prone mice, CCR1, CCR5, and their ligands are increased in the kidney during LN development." (PMID 27403037, 2016). "In lupus-prone NZB/W F1 mice, T cells and monocytes expressing CCR1 and CCR5 migrate to the kidney via sensing CCL3, CCL4, and CCL520." (PMID 37567910, 2023). "CCR1 deletion or specific CCR1 antagonism blunted the increased infiltration of macrophages and neutrophils observed in renal IRI and in a lupus-prone mouse model." (PMID 35743123, 2022). "Increased expression of CCR1 on PMN-MDSCs facilitates their entry into the circulation, as observed in systemic lupus erythematosus (SLE) mouse models." (PMID 30564242, 2018). "Therefore, it appears that CCR1 and CCR5 may, respectively, promote or attenuate the development of LN in lupus-prone mice." (PMID 27403037, 2016).
myocardial infarction (5 papers, 2013 to 2022). Gross necrosis of the myocardium, as a result of interruption of the blood supply to the area, as in coronary thrombosis. "In contrast, the induction of myocardial infarction in CCR1−/− and CXCR4−/− mice, which have reduced neutrophil recruitment, results in an increased or constant collagen content in the infarcted areas, despite preserved heart function and decreased infarction size." (PMID 36498897, 2022). "Intramyocardial injection of CCR1-overexpressing MSCs significantly increased the homing and engraftment to the injured area, prevented cardiac remodeling, and restored cardiac function 4 weeks after myocardial infarction." (PMID 32850943, 2020). "D6, an important member of the decoy receptor family, binds a broad range of CCR1, CCR2, and CCR5 ligands, prevents excessive infiltration of classical monocytes and neutrophils into the myocardium in a mouse model of myocardial infarction." (PMID 23417922, 2013).
narcolepsy (5 papers, 2017 to 2024). A sleep disorder characterized by a tendency for excessive sleepiness during the day which occurs even after adequate sleep in the nighttime. "There is limited evidence for a relationship between CCR1 and ISM, but genetic studies have found that a single-nucleotide polymorphism in CCR1 (rs3181077) was more prevalent in patients with early narcolepsy, which is a chronic neurologic sleep disorder." (PMID 39439987, 2024). "Reduced levels of microglia/macrophage-derived CCR1 and CCR3 are measured in peripheral blood samples from narcolepsy patients." (PMID 28912686, 2017). "A recent publication also reported reduced levels of the chemokine receptors CCR1 and CCR3 in peripheral blood samples of patients with narcolepsy." (PMID 28912686, 2017).
osteosarcoma (5 papers, 2008 to 2025). A usually aggressive malignant bone-forming mesenchymal neoplasm, predominantly affecting adolescents and young adults. "CCR1 is important for migration and invasion of osteosarcoma cells." (PMID 28300755, 2017). "Osteosarcoma cells polarized macrophages to an M2 phenotype via CSF1 and CSF1R, and interactions between LYVE1+ and angiogenic macrophages through CCL2 and CCR1 promoted a proangiogenic niche and inflammatory responses." (PMID 40647416, 2025). "CCR1, CCR2, CCR5, CCR7, CXCR4, CXCR5 and CX3CR1 were found to be expressed in 100% of the osteosarcoma samples tested." (PMID 18215331, 2008).
allergic disease (4 papers, 2018 to 2023). An immune response that occurs following re-exposure to an innocuous antigen, and that requires the presence of existing antibodies against that antigen. "Further investigation into the role of CCR1 in this mechanism may shed light on the etiology of allergy illnesses linked to eosinophils and possibly reveal novel targets for therapy." (PMID 37153575, 2023). "Although CCR1 has been regarded as a candidate target for autoimmune and allergic diseases for a long time, the success of CCR1-targeted drug development has been limited." (PMID 34949837, 2022). "CCR1 is widely expressed in various immune cells, and the knockdown of CCR1 has proved effective in suppressing the maturation and migration of immune cells, thus being regarded as an attractive drug target for the treatment of many autoimmune and allergic diseases, such as asthma." (PMID 34949837, 2022). "Although CCR1 and CCR3 are receptors for CCL13-induced eosinophil-triggered allergies, it is crucial to remember that CCR1 also has a function in CCL13-induced allergic pneumonia." (PMID 37153575, 2023). "Among the identified allergenic-related proteins, VIM was found to be involved in the progression of allergic diseases via inflammasome and VIM-P38MAPK complex facilitates mast cell activation via FcεRI/CCR1 activation." (PMID 34394070, 2021).
chronic obstructive pulmonary disease (4 papers, 2019 to 2024). A chronic and progressive lung disorder characterized by the loss of elasticity of the bronchial tree and the air sacs, destruction of the air sacs wall, thickening of the bronchial wall, and mucous accumulation in the bronchial tree. "Our research has uncovered the specific expression of CCR1 in macrophages, paralleling the observed increase in CCR1 expression on inflammatory cells in patients with severe chronic obstructive pulmonary disease (COPD)." (PMID 38716195, 2024). "Indeed, enhanced levels of CCR1 and/or CCR5 were shown to be present on monocytes from hemolytic uremic syndrome (HUS) or chronic obstructive pulmonary disease (COPD) patients, even though HUS or COPD monocytes did not respond as well as monocytes from healthy individuals in functional assays." (PMID 35222394, 2022).
endometriosis (4 papers, 2022 to 2025). The growth of functional endometrial tissue in anatomic sites outside the uterine body. "Although CCR1 has been implicated in renal ischemia, rheumatoid arthritis, endometriosis, and multiple sclerosis, its role in AMD remains unknown." (PMID 37903056, 2023). "In situ hybridization has demonstrated a doubling of CCR1 microRNA (miRNA) transcripts from peritoneal cells in endometriosis." (PMID 40003570, 2025).
nephritis (4 papers, 2010 to 2023). Inflammation of renal tissue. "Our finding that CCL3 inhibition enhances pathology is similar to the finding that in a model of nephritis CCR1−/− (the main receptor for CCL3) mice have enhanced pathology associated with increased TNF levels." (PMID 20195359, 2010). "Moreover, CCR1-deficient mice have enhanced macrophage and T cell infiltration to the glomerular region of the kidney in a nephrotoxic nephritis model, suggesting that such infiltration is CCR1-independent." (PMID 27403037, 2016). "In individuals with immunological thrombocytopenia, the expression of the Th1- and Th2-associated chemokine CCR3 gene was reduced, and animals lacking the chemokine receptor CCR1 had elevated Th1 responses and glomerular damage in nephritis." (PMID 36976996, 2023).
psoriasis (4 papers, 2010 to 2018). An autoimmune condition characterized by red, well-delineated plaques with silvery scales that are usually on the extensor surfaces and scalp. "In the psoriasis panel, CCR1 that plays a role in inflammatory response is associated with psoriasis via the analysis of skin lesion samples." (PMID 20444268, 2010). "CCL4L2, a ligand for CCR1 and CCR5 on macrophages and monocytes, is a polymorphism of CCL4L1, itself a non-allelic copy of CCL4 that differs in a single amino acid and all of which are associated with psoriasis severity." (PMID 29534074, 2018).
renal fibrosis (4 papers, 2015 to 2021). A final common manifestation of a wide variety of chronic kidney diseases characterized by glomerulosclerosis and tubulointerstitial fibrosis. "Analysis of UUO kidneys from Ccr1‐deficient mice revealed a reduction of renal fibrosis and interstitial lymphocytes compared with wild‐type controls." (PMID 33112058, 2020). "BX471, a CCR1 blocker, reduced renal fibrosis in mice of UUO by decreasing the T cell infiltration, which represented that blocking chemokines and respective receptors might be a potential therapeutic strategy for alleviating renal fibrosis." (PMID 34616308, 2021). "Blockade of MIP-1α/CCL3 receptor CC chemokine receptor CCR1 by antagonist molecule reduced interstitial infiltration of macrophages and T lymphocytes and renal fibrosis in kidneys of mice developing adriamycin-induced nephropathy with tubulointerstitial injury." (PMID 27219334, 2016). "Blockade of CCR1, a chemokine receptor for several ligands, including CCL3, 5, 7, 8, 14, 15, 16, and 232, by use of the antagonist BX471, was found to reduce cell accumulation and renal fibrosis in unilateral ureter obstruction." (PMID 26648169, 2015).
Behçet’s disease (3 papers, 2016 to 2023). "Low C-C chemokine receptor 1 (CCR1) and interleukin (IL)-10 expression is associated with risk of Behçet’s disease (BD)." (PMID 29895319, 2018).